HP (haptoglobin)
Diseases named in the same sentence as HP in open-access papers (continued):
Sharing a sentence is not in itself a finding about the gene and the disease.
tumor (continued). "The release of haptoglobin from the PLG scaffold increased the recruitment of tumor cells to the scaffold." (PMID 26634905, 2015). "From the six signature proteins (HLA-A, CFH, CD44, PTPRJ, HP, and CDH5), only CD44 has been previously associated with CRC prognosis in tumor specimens from 74 patients that were assayed by immunohistochemistry." (PMID 26253080, 2015). "The capability of haptoglobin to recruit tumor cells was tested in an orthotopic model of metastatic breast cancer." (PMID 26634905, 2015). "Serum levels of the IL-6 responsive acute phase reactants fibrinogen, haptoglobin and Von Willebrand Factor were also markedly induced in response to the tumor." (PMID 21799891, 2011). "CD163 functions as a hemoglobin-haptoglobin complex receptor and is associated with the “M2” or “pro-tumor” state of macrophages whereas normal microglia do not express CD163." (PMID 40191733, 2025). "We presume that the decreased expression of HP in tumor tissues may inhibit this regulatory pathway, thereby weakening the antioxidant and anti-inflammatory effects and promoting the development of SCLC." (PMID 39872525, 2024). "Moreover, low levels of HP expression are related to superior HCC tumor differentiation and enhanced five‐year overall survival in HCC patients." (PMID 38599581, 2024). "We identified novel HCC cell clusters that specifically express HP (HCC_HP), which may lead to higher tumor differentiation and tumor heterogeneity." (PMID 37914817, 2023). "In tumor cells, we found a subtype of interest HCC_HP, and analyzed HP positive cell type, observing a cluster of neutrophils (Neu_AIF1) that showed positive expression of the HP gene." (PMID 37914817, 2023). "Besides, co‐transfected with siTXN2 and HP overexpression vector significantly increased the size, volume of the tumour in vivo." (PMID 33528895, 2021). "Moreover, mEHT activated several stress response genes such as members of the heat shock response, complement factors such as C4, fibrinogens, haptoglobin and pentraxin, locally in the tumor." (PMID 33917524, 2021). "Some well-known tumor markers such as haptoglobin and CA 19-9 are fucosylated glycoproteins." (PMID 34881177, 2021). "It contains a large number of acute-phase proteins, such as α1-antitrypsin, α2-macroglobulin and haptoglobin, which may lead to tumor progression by damaging the immune system and changing the tumor microenvironment." (PMID 34234871, 2021). "The reason for this inconsistency could be because haptoglobin is mainly synthesized by the liver, and in addition to its secretion by tumor cells, other factors regulating its synthesis in the liver may regulate the content of haptoglobin in the blood." (PMID 31413735, 2019). "Haptoglobin can promote malignant transformation of epithelial cells and inhibit tumor immunity." (PMID 31413735, 2019). "The binding characteristic of haptoglobin to surface receptors of macrophages in the tumor microenvironment might play a crucial role for tumor cell growth and survival." (PMID 27725718, 2016). "Moreover, haptoglobin’s role in iron metabolism, particularly its ability to scavenge free haemoglobin, may also contribute to iron homeostasis in tumour cells, providing the conditions for uncontrolled cell proliferation." (PMID 40606553, 2025). "Moreover, results show that fucosylated Haptoglobin is produced by tumor cells." (PMID 24576319, 2014). "Specifically, genes such as TRIM71, DBH, HP, FER1L4, and GCH1 exhibited dynamic and progressive expression changes along tumor grades, with significant increases in Grade 4 tumors compared to Grade 1 (Wilcoxon test, adj." (PMID 41347690, 2025). "Furthermore, the modulation of haptoglobin could present an opportunity for targeted therapeutic strategies to reverse the tumour-promoting effects of haptoglobin while maintaining its essential functions in preventing oxidative damage and haemoglobin clearance." (PMID 40606553, 2025).
tumor (continued). "In the mice injected with chitosan nanoparticles loaded with recombinant HP-NAP, their survival rates and the rates of tumor shrinkage were higher than those in mice injected with recombinant HP-NAP alone." (PMID 36613542, 2022). "These mediators are responsible for the development and progression of the neoplasms; that is, PGE2 is responsible for tumor metastases, IL-6 for tumor invasion, and haptoglobin for implantation and angiogenesis." (PMID 36185863, 2022). "Some H. pylori virulence factors such as HP-NAP, have been applied as adjuvants or combined with drugs in pan-tumor treatment to improve immunotherapeutic efficiency." (PMID 35967444, 2022). "Interestingly, altered glycan content in some acute phase proteins, for example, haptoglobin, interact with a number of receptors on macrophages in the tumour microenvironment, potentially modulating macrophage activity and thereby contributing to tumour cell survival, growth, and metastasis." (PMID 29788918, 2018). "Plasma levels of haptoglobin, IL-6 and SAA correlated with the number of lung metastases in tumour-bearing mice." (PMID 29788918, 2018). "In fact, there was a high correlation between leukocyte number, IL-6, haptoglobin, SAA plasma concentration and a number of lung metastases in tumour-bearing mice." (PMID 29788918, 2018). "Despite advances in new methodologies, routine measurement of specific tumour markers remains challenging because some of them are rapidly degraded, difficult to assay and/or masked by highly abundant blood proteins like ALB, AAT, or HP." (PMID 35174082, 2022). "On the other hand, Haptoglobin level was shown to be affected by the amount of tumor burden and was not dependent on the histologic type or grade of ovarian malignancy." (PMID 31315664, 2019). "One study has also reported that haptoglobin could participate with STAT3 and HIF-1a in promoting angiogenesis and cell migration, and thus contributes to driving tumour growth and invasion." (PMID 31042781, 2019). "Haptoglobin level was shown to be affected by the amount of tumour burden and was not dependent on the histologic type or grade of ovarian malignancy." (PMID 15199385, 2004). "In their study, samples from three groups (PA, residual PA, and CXPA) were analyzed to identify protein signatures and their results suggested that seven proteins (APOA1, AP1M1, SYCP1, DCD, HBB, HP, and SLC4A1) could be potential signatures for tumor progression or suppression." (PMID 39155517, 2025). "Furthermore, the IHC analysis of human GC tissues from our cohort showed high levels of GNB4 protein in H. pylori-positive (HP+) tumor tissue samples compared to those in H. pylori-negative (HP−) samples (P < 0.05)." (PMID 37016382, 2023). "PLG scaffolds without haptoglobin recruited 13.1 ± 1.7 tumor cells to the implant site." (PMID 26634905, 2015). "Moreover, the potential of this work lies in the fact that we are proposing not just haptoglobin as biomarker, but to consider also the number of differential isoforms of alpha haptoglobin and their level of fucosylation present in the tumor tissue." (PMID 24576319, 2014). "We also detected 147 gene fusions in non-tumor liver tissues, many of which involved genes with extremely high expression values in liver tissues, such as ALB, HP, and TF, suggesting that detected fusion transcripts may also have originated from SVs harbored within minor sub-clonal liver cells." (PMID 25526364, 2014). "Western blotting analysis and immunohistochemistry of tumor tissues and normal tissues from patients with UTUC were carried out to further verify five possible UTUC biomarkers, including zinc-alpha-2-glycoprotein, calreticulin, annexin A2, annexin A3 and haptoglobin." (PMID 24884814, 2014).
cardiovascular disease (36 papers, 2009 to 2025). "Intensive glycemic control reduced coronary artery disease (CAD) events among the Action to Control Cardiovascular Disease Risk in Diabetes (ACCORD) participants with the haptoglobin (Hp) 2-2 phenotype only." (PMID 38402400, 2024). "Although the impact of this HP polymorphism on cardiovascular disease, including risk stratification, has been investigated in various studies, the results have been controversial and most of the studies were conducted in non‐Chinese population." (PMID 32794371, 2020). "Many of the identified proteins are known markers, risk factors, or proteins known to be involved in cardiovascular disease; e.g. transthyretin, apoA1, fibrinogen, serum amyloid A protein, haptoglobin, plasminogen, and others." (PMID 21631938, 2011). "Contrarily, the Hp2-allele has been linked to cardiovascular disease and the role of haptoglobin-genotype in asymptomatic SVD is unknown." (PMID 36856861, 2023). "Regarding the clinical significance of the different haptoglobin variants, it has been shown in longitudinal prospective studies that the Hp2-2 phenotype is an independent risk factor for the development of cardiovascular disease in diabetic individuals in comparison with the homozygous Hp1 variant." (PMID 35163309, 2022). "Another protein of interest is HP, which has been recognized as an inflammatory indicator in cardiovascular disease." (PMID 33260845, 2020). "For example, the ADIPOQ, AMY1A, CFB, HP and HBB are associated with the metabolic diseases, while the FBP4, HP, LPL and MYL2 are related to the cardiovascular diseases." (PMID 24204599, 2013). "Hp (Haptoglobin) has been reported to be strongly associated with infectious and non-infectious (e.g. cardiovascular diseases) diseases." (PMID 39546466, 2024). "Haptoglobin, alpha-1-antitrypsin and orosomucoid are reflected in the glycA signal, which has been shown to be an independent and more sensitive marker of inflammation and cardiovascular disease compared to CRP." (PMID 35413834, 2022). "A consequence of a haptoglobin increase is increased plasma abundance on an HFD, which may include increased risk for cardiovascular disease." (PMID 35327501, 2022). "Unfortunately, in the present study, we did not notice any significant differences in the occurrence of haptoglobin variants between patients with or without cardiovascular disease." (PMID 33114431, 2020). "These genes included: carbonic anhydrase 3 (Ca3), an enzyme known to contribute to cardiac hypertrophy and heart failure when expressed in the heart; haptoglobin (Hp), a biomarker of inflammation and cardiovascular disease (CVD); and heat shock protein 90 (Hsp90aa1)." (PMID 21338512, 2011). "Furthermore, haptoglobin-targeted therapies could play a role in cardiovascular diseases, where oxidative stress and inflammation contribute to atherosclerosis and thrombosis." (PMID 40606553, 2025). "Serum HP, CRP, B9, and B12 serve as indicators of various physiological processes and health conditions, including inflammation disorders, infections, hepatic and cardiovascular diseases, as well as the synthesis of neuroactive compounds." (PMID 39858234, 2025). "In the first part of the project, patients were divided into three groups which differed by the haptoglobin phenotype, and afterwards into two groups according to the criterion of the presence or absence of cardiovascular disease." (PMID 33114431, 2020). "Finally, forty years ago, clinicians were not using A2M, ApoA1 was interesting for predicting cardiovascular diseases, and haptoglobin was mostly used for the diagnosis of hemolysis." (PMID 35327501, 2022). "Furthermore, the key genes identified by MCODE analysis, HP, CXCL12, COL3A1, and PECAM1, may also serve as candidate targets for cardiovascular disease diagnosis." (PMID 32612856, 2020).
bacterial infection (25 papers, 2008 to 2025). "Within the last 20 years, haptoglobin has been used to study inflammation in domestic animals but has been more strongly associated with bacterial infections." (PMID 29375568, 2017). "Haptoglobin has been established as a valuable biomarker for various bacterial infections in cattle." (PMID 39943212, 2025). "A summary of linear models showing variation in the immune response to a mimicked bacterial infection (lipopolysaccharide challenge), measured as the change in haptoglobin concentration over c.17 h, in nestling Black Sparrowhawks." (PMID 36353782, 2023). "Consistently, the opposite pattern between lysis in unchallenged birds and haptoglobin response to a mimicked bacterial infection in this study suggests different strategies by urban versus less urban birds." (PMID 36353782, 2023). "A cell-free hemoglobin (Hb)-binding protein, haptoglobin (Hp), is an acute-phase protein in the blood that responds to bacterial infections and inflammation." (PMID 36296784, 2022). "Bacterial infection triggered cytokines production especially by neutrophils and macrophages which increased the rate of APPs production in general and haptoglobin in particular." (PMID 26961495, 2016). "For example, as the strongest activator of the hepatic acute-phase response, IL-6 mediates the secretion of a group of proteins, including C-reactive protein, serum amyloid A, haptoglobin, and α1-acid glycoprotein during bacterial infections." (PMID 27579592, 2016). "In the present study one ADLIB calf with elevated plasma haptoglobin had loose feces during second week of life and possibly suffered from a bacterial infection." (PMID 28036351, 2016). "The elevations in the CRP and haptoglobin concentrations were also consistent with bacterial infection and an inflammatory state." (PMID 23936104, 2013). "The sperm concentrations reached for SAA and haptoglobin during the BRSV-induced APR were generally the same or higher than bacterial infections in calves." (PMID 21430962, 2011). "The concentrations of APPs, including haptoglobin and serum amyloid A, are substantially increased in the peripheral plasma of cow with bacterial infection of the endometrium." (PMID 19017375, 2008). "BacSig was defined as the signature of the host response to bacterial infection using the average expression of five representative genes, including S100A12, CD177, HP, ANXA3, and ARG1." (PMID 38790931, 2024). "The hematologic markers that consistently showed statistically significant differences in bacterial versus non-bacterial infection patients were: polymorphonuclear leukocyte (PMN) counts, neutrophil counts, WBC counts, ESR, red blood cell (RBC) counts, lymphocyte counts, and haptoglobin." (PMID 27486746, 2016). "However, the negative correlation found between CP and HP gene expressions in both studied tissues may suggest their different iron-binding properties during bacterial infection in these two tissues." (PMID 32867772, 2020).
infectious disease (14 papers, 2012 to 2024). A disorder directly resulting from the presence and activity of a microbial, viral, or parasitic agent in humans. "An increase in HP concentrations can be caused by inflammation and infectious diseases and is associated with physical, psychological or environmental stress." (PMID 23866055, 2013). "Hp levels and HP rs72294371 ‘common polymorphism’ have been consistently associated with inflammatory-linked infectious and non-communicable diseases." (PMID 22403646, 2012). "Several studies suggest that haptoglobin polymorphisms may play an important role in the immune response against various infectious diseases because of their oxidizing action and immunomodulatory properties in other pathologies." (PMID 25147423, 2014). "Finally, correlations between HP genotypes in different age groups and cardiac manifestations suggest that HP polymorphism could influence the prognosis of this infectious disease." (PMID 25147423, 2014). "In studies investigating infectious diseases in pigs, haptoglobin has a longer period of elevation compared to other acute-phase inflammatory proteins, including CRP and pig-MAP." (PMID 38791689, 2024). "Blood levels of APP, such as SAA and haptoglobin, increase in the case of animals suffering from inflammatory or infectious diseases, but also in the case of stressed animals." (PMID 37756067, 2023). "It is important to have specific RIs for haptoglobin in young calves since it is an acute-phase protein used as biomarker of inflammatory and infectious diseases, very common in young calves." (PMID 31069239, 2019). "Haptoglobin also functions as a bacteriostatic agent, which increases rapidly during an infectious disease." (PMID 26202328, 2015). "By contrast, alpha-globulins such as haptoglobin, lipoproteins, and antitrypsin are important markers of acute inflammatory disease in some marine mammals and may be elevated in inflammatory and infectious diseases prior to clinical signs." (PMID 37443929, 2023). "In summary, we expect HPiP to interrogate changes in HP-PPIs which is vital for understanding complex infectious diseases, as well as prompt new testable hypotheses about the function of interacting proteins and their role in disease mechanisms." (PMID 35669347, 2022). "Moreover, acute-phase protein serum levels including α2-macroglobulin, haptoglobin, apolipoprotein A1 have been increased during the inflammatory reaction, and their components contribute to innate immune reaction against infectious diseases." (PMID 34422155, 2021). "SAA and HP are two major bovine acute phase proteins (APP), which are a group of stress proteins that regulate the inflammatory response, in vivo immune function and recovery mechanisms; their concentrations increase when animals are exposed to stress, such as inflammation and infectious diseases." (PMID 37508086, 2023).
respiratory disease (12 papers, 2011 to 2026). "Whereas higher haptoglobin concentrations have been observed in young calves with diarrhea or respiratory diseases, the anti-inflammatory properties of this acute-phase protein have also been documented." (PMID 40218414, 2025). "Inflammatory cytokines and haptoglobin (HPT) were measured from 28 head of cattle that presented with bovine respiratory disease after being purchased and shipped to a common feedlot and assigned to either control or metaphylaxis treatment groups." (PMID 41574260, 2025). "Blood samples were taken from calves with respiratory disease the first day of examination for determination of the serum concentration of haptoglobin, fibrinogen, α-2- and γ-globulins, and albumin." (PMID 21430962, 2011). "On arrival at the farm, 173 animals were checked for signs of BRD (e.g., coughing, tachypnea) and subjected to blood sampling to detect antibodies against common viruses related to respiratory diseases, and to measure levels of haptoglobin and reactive oxygen metabolites." (PMID 41012823, 2025). "Of these 52% of the investigations used an ELISA method from one manufacturer with a consistent calibration standard which gave reference range in healthy cattle of 0–0.15 mg/ml1 with a median haptoglobin concentration of 2.6 mg/ml in cattle with bovine respiratory disease." (PMID 31312640, 2019). "An increase in haptoglobin is typically expected as a result of respiratory disease, but the fact that levels were well above reference limits, which was already the case for INT calves at their point of origin in previous results, hints at other unknown causes." (PMID 39806431, 2025). "Research has shown that calves with respiratory system diseases have significantly higher concentrations of pro-inflammatory cytokines, SAA and HP in their serum compared to healthy calves, which is consistent with our study results." (PMID 37630463, 2023).